NMNAT1 (nicotinamide nucleotide adenylyltransferase 1)
Description:
Catalyzes the formation of NAD(+) from nicotinamide mononucleotide (NMN) and ATP. Can also use the deamidated form; nicotinic acid mononucleotide (NaMN) as substrate with the same efficiency. Can use triazofurin monophosphate (TrMP) as substrate. Also catalyzes the reverse reaction, i.e. the pyrophosphorolytic cleavage of NAD(+). For the pyrophosphorolytic activity, prefers NAD(+) and NaAD as substrates and degrades NADH, nicotinic acid adenine dinucleotide phosphate (NHD) and nicotinamide guanine dinucleotide (NGD) less effectively. Involved in the synthesis of ATP in the nucleus, together with PARP1, PARG and NUDT5. Nuclear ATP generation is required for extensive chromatin remodeling events that are energy-consuming. Also acts as a cofactor for glutamate and aspartate ADP-ribosylation by directing PARP1 catalytic activity to glutamate and aspartate residues on histones (By similarity). Fails to cleave phosphorylated dinucleotides NADP(+), NADPH and NaADP(+). Protects against axonal degeneration following mechanical or toxic insults (By similarity). Neural protection does not correlate with cellular NAD(+) levels but may still require enzyme activity (By similarity).
Synonyms: NMNAT; PNAT1; LCA9; SHILCA
Tractability: Small molecule: a structure with a bound ligand is known; it has a high-quality binding pocket. PROTAC: ubiquitination databases record sites on it; its protein half-life has been measured.
Target class: Enzyme; Transferase
Gene: Protein-coding gene on chromosome 1 (9,943,428 to 9,985,501, forward strand). Ensembl gene ENSG00000173614.
Subcellular location: Nucleus
Subcellular location (Human Protein Atlas): Nuclear bodies; Nucleoplasm
Pathways (Reactome):
Metabolism: Nicotinate metabolism
Gene Ontology:
Molecular function: identical protein binding; nicotinamide-nucleotide adenylyltransferase activity; nicotinate-nucleotide adenylyltransferase activity; protein binding; protein ADP-ribosyltransferase-substrate adaptor activity; catalytic activity; nucleotidyltransferase activity
Biological process: ATP generation from poly-ADP-D-ribose; NAD+ biosynthetic process via the salvage pathway; negative regulation of DNA-templated transcription; nucleotide biosynthetic process; NAD+ biosynthetic process; purine nucleotide metabolic process
Cellular component: nuclear body; nucleoplasm; nucleus; chromatin
Genetic constraint (gnomAD): Loss-of-function variants: 17 observed, 19.44 expected, observed/expected ratio (o/e) 0.87, 90% interval 0.6 to 1.31. The upper end of that interval is the gene's LOEUF score, 1.31, which puts it in group 5 of 6, group 1 being the genes least tolerant of losing a copy. Missense variants: 241 observed, 300.69 expected, observed/expected ratio (o/e) 0.8, 90% interval 0.72 to 0.89. Synonymous variants: 95 observed, 109.16 expected, observed/expected ratio (o/e) 0.87, 90% interval 0.74 to 1.03.
Gene-disease validity (ClinGen):
ClinGen rates the evidence that NMNAT1 causes each of these diseases.
NMNAT1-related retinopathy (autosomal recessive): Definitive. A retinopathy, typically severe and early onset, caused by biallelic variants in the NMNAT1 gene.
Homologues: Orthologues: chimpanzee NMNAT1 (99% identical), macaque NMNAT1 (97% identical), dog NMNAT1 (86% identical), pig NMNAT1 (85% identical), rat Nmnat1 (83% identical), mouse Nmnat1 (82% identical), guinea pig NMNAT1 (78% identical), zebrafish nmnat1 (58% identical). Paralogues in human: NMNAT3 (46% identical), NMNAT2 (39% identical).
Diseases named in the same sentence as NMNAT1 in open-access papers:
NMNAT1 is named in the same sentence as 77 diseases in open-access papers, as found by Europe PMC text mining. Sharing a sentence is not in itself a finding about the gene and the disease. The quoted sentences say what the papers report.
Leber congenital amaurosis (15 papers, 2013 to 2026). Leber congenital amaurosis (LCA) is a retinal dystrophy defined by blindness and responses to electrophysiological stimulation (Ganzfeld electroretinogram (ERG)) below threshold, associated with severe visual impairment within the first year of life. "Early-onset inherited retinal degenerations (IRDs), such as Leber congenital amaurosis (LCA) caused by pathogenic variants in the NMNAT1 gene, lead to severe vision loss in children." (PMID 41922335, 2026). "This study delves into the genetic basis of Leber congenital amaurosis, pinpointing compound heterozygous mutations in the NMNAT1 gene as significant causative factors." (PMID 39445201, 2024). "This question is of importance as multiple mutations in NMNAT1 have been identified in patients with Leber congenital Amaurosis (LCA), another neurodegenerative disease targeting photoreceptors." (PMID 35663397, 2022). "Previous studies show that mutations in NMNAT1 cause Leber congenital amaurosis and white matter disorders." (PMID 33671795, 2021). "Although attempts to replenish NAD+ content with NA in fibroblasts from a patient with Leber congenital amaurosis caused by NMNAT1 mutations were unsuccessful, the potential of other NAD+‐boosting molecules warrants further research." (PMID 34041853, 2021). "Leber congenital amaurosis 9 (LCA9) is an autosomal recessive retinal degeneration condition caused specifically by mutations in NMNAT1, a key NAD+ biosynthetic enzyme." (PMID 32454935, 2020). "Moreover, NMNAT1 is important in retinal development and physiology, and NMNAT1 mutations are linked to the occurrence of detrimental retinal degenerative conditions such as Leber congenital amaurosis." (PMID 38396769, 2024). "The discovery that loss-of-function mutations in the nuclear isoform NMNAT1 cause Leber Congenital Amaurosis (LCA), a human nervous system disorder characterized by degeneration of retinal neurons and blindness, directly links NMNAT1 to neuron survival." (PMID 29175372, 2018). "Leber congenital amaurosis (LCA) is a severe, genetically heterogeneous dystrophy of the retina and mutations in the nicotinamide mononucleotide adenylyltransferase 1 (NMNAT1) gene is one of causal factors of LCA." (PMID 30166529, 2018). "Mutations in NMNAT1 were reported to cause Leber congenital amaurosis (LCA), one of the IRDs." (PMID 35624805, 2022). "Direct acknowledgement of NAD+ retina related pathology comes from studies on Leber congenital amaurosis 9 (LCA9), a very severe retinal dystrophy that lead to complete vision loss caused by mutations in NMNAT1." (PMID 32961812, 2020). "Remarkably, several recent studies have shown that, in humans, mutations in NMNAT1 result in lower levels of NAD+ and have been associated with Leber congenital amaurosis, a severe form of inherited blindness." (PMID 26618989, 2015). "Specifically, we detected pathogenic DNA variants (∼50% novel mutations) in the genes RP1, USH2A, CNGB3, NMNAT1, CHM, and ABCA4, responsible for retinitis pigmentosa, Usher syndrome, achromatopsia, Leber congenital amaurosis, choroideremia, or recessive Stargardt/cone-rod dystrophy cases." (PMID 23940504, 2013).
retinal degeneration (10 papers, 2008 to 2026). Degeneration of the retina. "It has been reported that NMNAT1 was implicated in the pathological progress of retinal degeneration, axonal degeneration, tauopathy, and ischemic stroke." (PMID 40577472, 2025). "Nmnat1 gene therapy has shown protective effects against glaucomatous neurodegeneration and Nmnat1-associated retinal degeneration in mice models." (PMID 38396769, 2024). "As the first target, we chose NMNAT1, in which bi-allelic pathogenic variants lead to early-onset retinal degeneration." (PMID 39795970, 2024). "Another example is NMNAT1–associated retinal degeneration, a recessive disease that causes severe vision loss during the first or second decade of life." (PMID 34198948, 2021). "Consistent with this notion, pan-retinal NMNAT1 deletion is shown to cause rapid and severe retinal degeneration in mice shortly after birth." (PMID 34878972, 2021). "Collectively, our study reveals previously unrecognized complexity in NMNAT1-associated retinal degeneration and suggests a yet-undescribed role for NMNAT1 in gene regulation during photoreceptor terminal differentiation." (PMID 34878972, 2021). "A gene replacement attempts on a mouse model with retinal degeneration were performed for NMNAT1 and CRB1 genes, also associated with LCA in a studied group of Polish patients." (PMID 33308271, 2020). "Using NMNAT1 conditional mutant mice, we showed that photoreceptors degenerate rapidly after the loss of NMNAT1 and that depletion of NMNAT1 in rod or cone cells is necessary and sufficient for the retinal degeneration." (PMID 33107823, 2020). "We next sought to determine the molecular mechanisms required for retinal degeneration in the NMNAT1-deficient retina." (PMID 33107823, 2020). "Since the loss of NMNAT1 induced retinal degeneration, we wished to determine the role of NMNAT2 and 3 in the retinal structure/function." (PMID 33107823, 2020). "Yet, despite its essential role, NMNAT1 mutations cause retinal degeneration exclusively." (PMID 39795970, 2024). "Furthermore, within ophthalmology, NMNAT1 mutations (LCA9 gene) have been linked to retinal degeneration in Leber’s congenital amaurosis in humans." (PMID 34198948, 2021). "In sum, we show that retinal NMNAT1 loss activates multiple cell death pathways, which contextualizes the degeneration of multiple cell types in our model and may explain the severity of NMNAT1-associated retinal degeneration in this study and others." (PMID 34878972, 2021). "Loss of NMNAT1 leads to early and severe retinal degeneration." (PMID 34878972, 2021). "We next asked whether AAV-mediated expression of HA-tagged human NMNAT1 could prevent retinal degeneration caused by Nmnat1 excision." (PMID 33107823, 2020). "In summary, these genetic ablation experiments demonstrate the importance of NMNAT1 for proper function and survival of both rods and cones, and indicate that LCA9-associated retinal degeneration is likely due to the direct cell-autonomous effects of NMNAT1 mutations in photoreceptors." (PMID 33107823, 2020). "Hence, mutations in NMNAT1 may promote retinal degeneration through the direct impact on NAD+ biosynthesis and/or through the regulation of the SARM1-dependent degenerative program." (PMID 33107823, 2020). "To identify possible mechanisms for the severe and cell-type-specific retinal degeneration in our model, we next sought to characterize global metabolic consequences of embryonic NMNAT1 deletion in the retina." (PMID 34878972, 2021). "In general, this phenotype is consistent with several recent studies reporting partial or complete ablation of retinal NMNAT1, which report gross retinal degeneration beginning within the first postnatal week and largely complete by one month of age." (PMID 34878972, 2021). "Overall, these metabolomics results suggest specific disruptions to central carbon, purine nucleotide, and amino acid metabolism as potential causes for severe retinal degeneration in the absence of NMNAT1." (PMID 34878972, 2021).
retinal degeneration (continued). "Mice harboring Nmnat1 mutations (V9M and D243G) exhibit severe retinal degeneration while the most common LCA9 mutation (E257K), which is not fully penetrant, induces a milder retinal degeneration phenotype." (PMID 33107823, 2020). "In addition, cell-type specific deletion of NMNAT1 in early postnatal photoreceptors is sufficient to induce retinal degeneration." (PMID 33107823, 2020). "Photoreceptor-specific depletion of NMNAT1 induces retinal degeneration." (PMID 33107823, 2020). "NMNAT1 is indispensable for mouse development and recent studies identified causative mutations in NMNAT1 in patients with Leber congenital amaurosis type 9 (LCA9), a disorder associated with severe, early-onset retinal degeneration and vision loss." (PMID 33107823, 2020). "Despite the ubiquitous expression of NMNAT1, patients do not manifest pathologies other than retinal degeneration." (PMID 33107823, 2020). "While NMNAT1 gene replacement is a potential treatment option for LCA9, if SARM1 plays a more general role in retinal degeneration, then using gene therapy to express this dominant negative SARM1 could not only treat LCA9, but also multiple retinal neurodegenerative diseases." (PMID 33107823, 2020).
glaucoma (8 papers, 2017 to 2024). Increased pressure in the eyeball due to obstruction of the outflow of aqueous humor. "A recent study showed reductions in Nampt, Nmnat1, and Nmnat2 in RGCs in glaucoma patients, implying that not only the NAD+ level but also the NAD salvage pathway can be reduced in glaucoma." (PMID 37754233, 2023). "This pattern was also evident for NMNAT1 (n = 10 control eyes, 5 glaucoma eyes) and NMNAT2 (n = 8 control eyes, 5 glaucoma eyes)." (PMID 36681854, 2023). "Strategies used to protect against axon degeneration in glaucoma in particular consist of providing glucose, upregulating NMNAT1 and NMNAT3, providing ketone bodies, and inhibiting histone deacetylases (HDACs)." (PMID 28424571, 2017). "Our group has previously demonstrated that overexpression of murine Nmnat1 also protects from glaucoma." (PMID 28487632, 2017). "Restoration of NAD, using a diet supplemented in nicotinamide (NAM; an NAD precursor), or through gene therapy (over expression of Nmnat1; coding an NAD producing enzyme), protects from glaucoma." (PMID 28487632, 2017). "NMNAT1 was significantly reduced in the GCC and INL in both central and mid-peripheral retina, with no detectable difference in the outer retina (n = 11 control eyes, 7 glaucoma eyes)." (PMID 36681854, 2023). "As such, both NMNAT1 and NMNAT2 may be valid treatment targets in the context of glaucoma and optic neuropathies." (PMID 36681854, 2023). "Indeed, dietary supplement of NAD precursor nicotinamide (a form of vitamin B3) or overexpression of nicotinamide nucleotide adenylyltransferase 1 (NMNAT1) that is a key NAD-producing enzyme, prevented metabolic breakdown and rescued RGCs in mouse glaucoma." (PMID 34199494, 2021). "Although glaucoma may be uniquely sensitive to WLDS mediated protection, our current data raise the possibility of combining WldS (and/or Nmnat1) gene therapy with NAM administration in other neurodegenerative conditions." (PMID 28487632, 2017).
Leber congenital amaurosis 9 (7 papers, 2015 to 2024). Any Leber congenital amaurosis in which the cause of the disease is a mutation in the NMNAT1 gene. "This holds clinical relevance as LoF mutations in NMNAT1 underlie Leber congenital amaurosis type 9 (LCA9)." (PMID 38538779, 2024). "To date, over 30 NMNAT1 mutations have been linked to the severe blinding diseases Leber congenital amaurosis type 9 (LCA9) and related cone-rod dystrophy." (PMID 34878972, 2021).
Blindness (5 papers, 2015 to 2023). Blindness is the condition of lacking visual perception defined as a profound reduction in visual perception. "Recent studies have revealed that NMNAT1 appears to have neuroprotective properties in the retina, brain, and central nervous system, and mutations in NMNAT1 have been identified to cause a non-syndromic early form of blindness." (PMID 31590397, 2019).
retinal disease (5 papers, 2019 to 2024). "Most of the disease-associated genes were unique to a single retinal disease, with the exception of Abca4, Nmnat1, Casp3, and Crb1, which were each shared across two diseases." (PMID 31527661, 2019). "To test the PE technology in hiPSCs with relevance to retinal disease, we chose three IRD genes with ubiquitous expression but associated with an isolated retinal phenotype NMNAT1, PRPF3, and PRPF8." (PMID 39795970, 2024).
Alzheimer disease (4 papers, 2020 to 2026). A progressive, neurodegenerative disease characterized by loss of function and death of nerve cells in several areas of the brain leading to loss of cognitive function such as memory and language. "The insights obtained from this stratified examination extend to potential age-related biomarkers associated with the risk of Alzheimer’s disease (AD), such as the reduced expression of NMNAT1." (PMID 38472245, 2024). "Studies in a mice model of Alzheimer disease have linked NMNAT1 to protection against Alzheimer disease." (PMID 32984236, 2020). "In Alzheimer's disease (AD), NMNAT1 overexpression facilitates amyloid clearance through autophagy activation." (PMID 41521645, 2026).
breast carcinoma (4 papers, 2016 to 2022). "Activated PARP1 then rapidly generates poly-ADP-ribose (PAR) from NAD+ synthesized within the cell nucleus by NMNAT1 (Nicotinamide Nucleotide Adenylyltransferase 1) within the nucleus of breast cancer cells." (PMID 31510016, 2019). "The impact of H2S on NAMPT/SIRT1, likely, has global effects since it has been shown that RNA-mediated knockdown of NAMPT or NMNAT-1 in MCF-7 breast cancer cells reduced total cellular NAD+ levels and globally altered pattern of gene expression." (PMID 27732642, 2016).
Diabetic Nephropathy (3 papers, 2022 to 2025). "More specifically, high BB-DNA levels could be considered a biomarker of diabetic nephropathy, as they have been associated with increased methylation levels of VEGFA and NMNAT1, key contributors to the progression of diabetic kidney disease." (PMID 40724814, 2025). "In short, the results of this study provided the first evidence that NMN accumulation, possibly induced by up-regulation of NAMPT and down-regulation of NMNAT1 in diabetic nephropathy, plays a pathogenic role in DN with regulatory effects on NF-κB P65 and Sirt1 signaling pathways." (PMID 35408818, 2022).
glioma (3 papers, 2012 to 2023). A benign or malignant brain and spinal cord tumor that arises from glial cells (astrocytes, oligodendrocytes, ependymal cells). "We excluded four genes (SLCO3A1, C10orf11, PTPRJ, and NMNAT1) from further analysis because the direction of association of additional tested SNPs with glioma risk was inconsistent with our hypothesis." (PMID 23091480, 2012). "NMNAT1 was found significantly upregulated in gliomas (p<0.001) compared to controls and in HGG (p<0.001) compared to LGG patients." (PMID 36809279, 2023). "We next examined the function of NMNAT in human glioma cell proliferation, specifically human NMNAT1 (nuclear) and NMNAT2 (cytoplasmic)." (PMID 34919052, 2021). "In our study NAMPT, NMNAT1 and NMNAT3 were found significantly upregulated in glioma samples compared to the controls." (PMID 36809279, 2023). "Oncometabolic rate assessment analysis showed significant increased ATP level (p<0.0001), NAD+ level [(NMNAT1 (p<0.0001), NMNAT3 (p<0.0001) and NAMPT (p<0.04)] and glutathione level (p<0.0001) in glioma patients compared to controls." (PMID 36809279, 2023). "In the aggressive form of glioma, glioblastoma multiforme (GBM), from which the T98G and U87MG cell lines are derived, high NMNAT1-expressing tumors (top 10%) again showed a significant correlation with more aggressive disease and poorer outcome." (PMID 34919052, 2021). "We determined NMNAT1 and NMNAT2 protein levels in human glioma cells and normal astroglia cells (SVG p12)." (PMID 34919052, 2021). "Compared to SVG p12 cells, NMNAT1 and NMNAT2 are increased in both glioma cells T98G and U87MG." (PMID 34919052, 2021).